KANSL2 (KAT8 regulatory NSL complex subunit 2)
Description:
Non-catalytic component of the NSL histone acetyltransferase complex, a multiprotein complex that mediates histone H4 acetylation at 'Lys-5'- and 'Lys-8' (H4K5ac and H4K8ac) at transcription start sites and promotes transcription initiation. Required for NSL complex stability and for transcription of intraciliary transport genes in both ciliated and non-ciliated cells by regulating histone H4 acetylation at 'Lys-5'- and 'Lys-12' (H4K5ac and H4K12ac) (By similarity). This is necessary for cilium assembly in ciliated cells and for organization of the microtubule cytoskeleton in non-ciliated cells (By similarity). Required within the NSL complex to maintain nuclear architecture stability by promoting KAT8-mediated acetylation of lamin LMNA (By similarity).
Synonyms: C12orf41; NSL2; FLJ20436
Tractability: Antibody: its Gene Ontology location is reachable by antibodies, with high confidence; the Human Protein Atlas places it where antibodies can reach. PROTAC: UniProt records ubiquitination sites on it; ubiquitination databases record sites on it; its protein half-life has been measured.
Gene: Protein-coding gene on chromosome 12 (48,653,211 to 48,682,247, reverse strand). Ensembl gene ENSG00000139620.
Subcellular location: Nucleus; Mitochondrion
Subcellular location (Human Protein Atlas): Cytosol; Nucleoplasm; Plasma membrane
Pathways (Reactome):
Chromatin organization: HATs acetylate histones
Gene expression (Transcription): Formation of WDR5-containing histone-modifying complexes
Gene Ontology:
Molecular function: protein binding
Biological process: positive regulation of DNA-templated transcription
Cellular component: cytosol; histone acetyltransferase complex; NSL complex; nucleoplasm; nucleus; plasma membrane; mitochondrion
Genetic constraint (gnomAD): Loss-of-function variants: 32 observed, 45.48 expected, observed/expected ratio (o/e) 0.7, 90% interval 0.53 to 0.94. The upper end of that interval is the gene's LOEUF score, 0.94, which puts it in group 4 of 6, group 1 being the genes least tolerant of losing a copy. Missense variants: 482 observed, 578.05 expected, observed/expected ratio (o/e) 0.83, 90% interval 0.77 to 0.9. Synonymous variants: 202 observed, 206.83 expected, observed/expected ratio (o/e) 0.98, 90% interval 0.87 to 1.1.
Homologues: Orthologues: chimpanzee KANSL2 (99% identical), macaque KANSL2 (98% identical), pig KANSL2 (96% identical), rabbit KANSL2 (96% identical), mouse Kansl2 (94% identical), rat Kansl2 (94% identical), dog KANSL2 (91% identical), guinea pig KANSL2 (89% identical), tropical clawed frog kansl2 (72% identical), zebrafish kansl2 (59% identical), Drosophila melanogaster dgt1 (34% identical).
Diseases named in the same sentence as KANSL2 in open-access papers:
KANSL2 is named in the same sentence as 9 diseases in open-access papers, as found by Europe PMC text mining. Sharing a sentence is not in itself a finding about the gene and the disease. The quoted sentences say what the papers report.
glioblastoma (3 papers, 2019 to 2026). The most malignant astrocytic tumor (WHO grade IV). "Together, these findings identify KANSL2 as a nuclear factor that transiently associates with nucleoli to promote rRNA transcription and ribosome biogenesis, supporting the biosynthetic and proliferative capacity of glioblastoma cells." (PMID 41787092, 2026). "Consistently, reduced KANSL2 levels result in smaller tumors after transplantation of KANSL2‐depleted glioblastoma cells into immunodeficient mice." (PMID 31267707, 2019). "KANSL2 was shown to drive the stem cell‐like features of glioblastoma cells, and knockdown of KANSL2 reduced expression of the pluripotency factors NANOG and POU5FI, while it increased the expression of the neural differentiation markers TUBB3 and GFAP95." (PMID 31267707, 2019). "KANSL2 gene encodes the KAT8 regulatory NSL complex subunit 2 protein, which is a KANSL protein family member belonging to the complex of lysine acetyl-transferase KAT8/MOF-NSL, and recently shown to regulate glioblastoma’s cancer stem-like properties that contribute to tumorigenesis." (PMID 32001790, 2020). "KANSL2 is a subunit of the non-specific lethal (NSL) chromatin-modifying complex associated with glioblastoma (GBM) progression, but the intrinsic role of KANSL2 in GBM cells is poorly understood." (PMID 41787092, 2026).
Intellectual disability (2 papers, 2019). "Underpinning its importance, loss of NSL complex members leads to lethality during early development in flies, whereas heterozygous mutations in NSL1 and NSL2 orthologs KANSL1 and KANSL2 underlie intellectual disability in humans." (PMID 30819819, 2019).
cholangiocarcinoma (1 paper, 2022). A carcinoma that arises from the intrahepatic biliary tree (intrahepatic cholangiocarcinoma) or from the junction, or adjacent to the junction, of the right and left hepatic ducts (hilar cholangiocarcinoma). "Additionally, the discovery that KANSL2 modulates cholangiocarcinoma cell invasion is manifested." (PMID 35191804, 2022).
cancer (2 papers, 2020 to 2022). A tumor composed of atypical neoplastic, often pleomorphic cells that invade other tissues. "KAT8 of KANSL2 gene encoding, a member of the KANSL protein family, modulates the NSL complex subunit 2 protein belonging to the KAT8/MOF-NSL complex, and it has been discovered to be associated with cancer and neurodevelopmental disorders." (PMID 35191804, 2022). "Antecedent researches have elucidated that KANSL2 is elevated in GBM, which accelerates tumorigenesis via mediating GBM’s cancer stem cell-like characteristics." (PMID 35191804, 2022). "Our findings that MBNL3 and KANSL2 regulate PDAC cell invasion add to the growing knowledge that MBNL3 and KANSL2 play important roles in cancer metastasis, and warrant further investigation to define the underlining mechanisms in order to validate them as potential therapeutic targets for PDAC." (PMID 32001790, 2020).
tumor (1 paper, 2022). "In short, Rop exerted an anti-tumor impact on GBM via mediating the miR-21-5p/KANSL2 axis, which offered novel viewpoints for the later adoption of Rop as GBM drugs." (PMID 35191804, 2022).
KANSL2 also shares sentences with these, for which no sentence is quoted: breast carcinoma (1 paper); ischemic heart disease (1); neurodevelopmental disorder (1); pancreatic ductal adenocarcinoma (1).